IDH1 (isocitrate dehydrogenase (NADP(+)) 1)
Diseases named in the same sentence as IDH1 in open-access papers (continued):
Sharing a sentence is not in itself a finding about the gene and the disease.
glioblastoma (continued). "The number of blood samples drawn from glioblastoma patients operated at BWH was estimated to be 3.7-fold higher compared to patients from UMCU after correction for age, sex, IDH1 mutation status, postoperative KPS score, length of stay, and survival status." (PMID 34997355, 2022). "A similar single-cell RNA-sequencing approach revealed a bone marrow-derived macrophage subpopulation that drives tumor progression in the IDH1-wild-type glioblastomas." (PMID 36430704, 2022). "All the three long-term surviving patients were females younger than 70 years with good performance scores (KPS ≥ 70), and two of them had a histologically confirmed IDH1 wildtype glioblastoma." (PMID 35892046, 2022). "On the other hand, some molecular alterations associated with neurological tumors have already been detected in plasma cfDNA, such as the number of MYCN copies in neuroblastoma or specific somatic mutations in glioblastoma (EGFR and IDH1)." (PMID 35563270, 2022). "Pathological analysis showed that CIMP was common in low-malignant oligodendroglioma (OR 5.51; 95% CI 3.95–7.70) with molecular features including IDH1 mutations and 1p19q LOH, but rare in glioblastoma (OR 0.14; 95% CI 0.10–0.19)." (PMID 36181110, 2022). "We evaluated their expression using five paraffin-embedded pediatric glioblastomas (with WT genotype for IDH1/2 and H3F3A genes) and two paraffin-embedded healthy cerebrums." (PMID 36293551, 2022). "The IDH1 mutation was traced in all cases of oligodendrogliomas and astrocytoma’s of grade II-III as well as in the secondary grade IV glioblastomas." (PMID 35625744, 2022). "Mutant IDH1 mRNA was identified in CSF-derived exosomes of patients bearing mutant IDH1 glioblastoma and higher level of IDH1 mRNA was found in exosomes from patients with tumors than healthy controls." (PMID 35180868, 2022). "Here, we describe the effects of heterozygous IDH1R132H on the redox system in a CRISPR/Cas edited glioblastoma model and compare them with IDH1 wild-type (IDH1wt) cells." (PMID 35628596, 2022). "We chose two glioblastoma cases with known mutations in BRAF (V600E) and IDH1 (R132H), respectively." (PMID 35937639, 2022). "The newly updated 2021 WHO Classification of Tumors of the Central Nervous System distinguished glioblastoma in wild-type and mutant IDH1/2." (PMID 35884887, 2022). "According to WHO CNS 2016 classification, NULU and ZAR are IDH1 wild-type glioblastoma cell lines with unmethylated MGMT promoter genes, leading to a drug-resistant phenotype." (PMID 35458581, 2022). "This is most probably due to the fact that TCGA sampling included mainly the primary glioblastoma cases, i.e., IDH1/2 wildtype." (PMID 36613601, 2022). "IDH1 missense mutation in codon 132 was confirmed for the astrocytoma and oligodendroglioma cases, and IDH-wildtype status was confirmed for 13 glioblastomas." (PMID 36613601, 2022). "When comparing IDH1-mut versus IDH1-WT glioblastoma (comparison III), we identified 16 pathway changes." (PMID 34941573, 2022). "The ROC analysis revealed the high sensitivity and specificity of this technique in the differential diagnosis of glioblastomas with different IDH1 statuses." (PMID 35741254, 2022). "These metabolic differences between IDH1-WT (increased glutamate, citrate) and IDH1-mut glioblastoma (decreased glutamate, citrate) reflect different clinical outcome of these entities." (PMID 34941573, 2022). "The results from Kaplan-Meier plot showed that IDH1 mutation was associated with better OS in LGG and glioblastoma." (PMID 35982398, 2022). "The present investigation aimed to analyze the influence of AEDs, and in particular levetiracetam, on the presence and quality of visible 5-ALA fluorescence in surgery for IDH1 wild-type glioblastoma." (PMID 35565263, 2022).
glioblastoma (continued). "Low GLUD1 levels in IDH1-WT glioblastoma, thus, correlate well with increased glutamate tissue levels." (PMID 34941573, 2022). "IDH1 or IDH2 mutations have been shown to be present in about 80% of grade II and grade III LGG and previously designated “secondary glioblastomas” (HGG)." (PMID 34277415, 2021). "Although methylated MGMT promoter with IDH1 mutant glioblastoma cases showed clinically significant results, the cases with unmethylated MGMT promoter and IDH1 mutation treated with combined chemotherapies had significantly late tumor recurrence." (PMID 34257620, 2021). "IDH1 wild-type tumors are also more common in elderly patients, partly explaining the age-dependent prognosis of glioblastoma survival." (PMID 33742279, 2021). "In this work, we demonstrate that inactivation of KDM4B, through H3.3G34R or IDH1/2 mutations, acts in tandem with ATRX mutations to promote ALT in glioblastomas." (PMID 33972520, 2021). "For example, we found that more glioblastoma patients younger than 50 years old with IDH1 mutant tumors had tumor recurrence after one year of treatment compared with those with IDH1 wildtype." (PMID 34257620, 2021). "The Ivy Glioblastoma Atlas contains a total of 41 glioblastoma patients, of whom 34 had IDH1 wildtype primary glioblastoma." (PMID 34359668, 2021). "Wnt/β-catenin signaling was also identified to be involved in the inhibition of cell proliferation, migration and invasion in IDH1 mutant glioblastoma cell lines." (PMID 34516556, 2021). "This means that glioblastoma with wildtype IDH1 and unmethylated MGMT promoter should be treated aggressively with combined chemotherapies (TMZ plus other chemotherapies) to improve overall survival." (PMID 34257620, 2021). "Unsupervised clustering revealed a pro-tumor subpopulation of bone marrow-derived macrophages characterized by the scavenger receptor MARCO, which is almost exclusively found in IDH1-wild-type glioblastomas." (PMID 34011400, 2021). "First, we review the present state of affairs with respect to energy metabolism in differentiated glioblastoma cells that are IDH1 wild-type (IDH1wt) or IDH1mt." (PMID 33810170, 2021). "The long-term survival of LPE + glioblastoma cases suggests a potential correlation between LPE + status and IDH1 mutation or MGMT promotor methylation status." (PMID 34459971, 2021). "The association between IDH1 mutation and MGMT methylation status with recurrence-free interval within 3 years among glioblastoma patients treated with radiotherapy or chemoradiotherapy." (PMID 34257620, 2021). "Glioblastomas (GBM) differ at the genetic and epigenetic levels, especially with the distinguishing feature in the identification of mutations in the metabolic enzyme isocitrate dehydrogenase 1 (IDH1)." (PMID 34070746, 2021). "The IDH1 gene, which encodes cytosolic NADP + -dependent isocitrate dehydrogenase, was shown to correlate with outcome of patients with glioblastoma." (PMID 34257620, 2021). "Patients harboring an IDH-1 wildtype glioblastoma presented with an increased preoperative edema to tumor ratio; however, further translational investigations are warranted to elucidate the underlaying mechanism." (PMID 33868245, 2021). "Use of IDH1 combined with MGMT promoter as a stratification factor seems appropriate in clinical trials for the treatment of patients with secondary glioblastoma." (PMID 34257620, 2021). "This study highlights the essential role of glutamine metabolism in glioblastoma cells and provides a potential therapeutic opportunity to target glutamine metabolism in IDH1/2 mutant cancers." (PMID 33681764, 2021). "We identified 19 diffuse astrocytomas, 67 anaplastic astrocytomas and 143 glioblastomas, all harboring IDH1/2 wildtype genotypes." (PMID 34162860, 2021). "This revealed that IDH1 mutation and MGMT methylation are independent prognostic factors in glioblastoma." (PMID 34257620, 2021).
glioblastoma (continued). "The expression of miR-411 was significantly reduced in glioblastoma, which was associated with the Karnofsky Performance Score (KPS) and Isocitrate dehydrogenase 1 (IDH1) status of patients." (PMID 34606414, 2021). "On the other hand, the present MET fractal dimension showed a significant difference between IDH1-mutant and IDH1-wildtype in diffuse astrocytoma and anaplastic astrocytoma and IDH1-mutant diffuse astrocytoma and anaplastic astrocytoma and glioblastoma." (PMID 34743250, 2021). "Our results concluded that IDH1 mutation and MGMT gene promoter methylation are considered independent prognostic factors in glioblastoma." (PMID 34257620, 2021). "In the present study, MET SUVmax and T/N ratio in glioblastoma were significantly higher than those in IDH1-mutant diffuse astrocytoma and anaplastic astrocytoma." (PMID 34743250, 2021). "Autologous chimeric antigen receptor (CAR) T cells targeted to epidermal growth factor receptor variant III (CAR T-EGFRvIII) have been developed and administered experimentally to treat patients with IDH1 wildtype recurrent glioblastoma (rGBM) (NCT02209376)." (PMID 34026647, 2021). "Forty-three patients with primary, isocitrate dehydrogenase 1 (IDH1) wild type glioblastomas (GBMs) were included in this study." (PMID 34298788, 2021). "Radiologic features (n = 35 340) were extracted from 46 multisequence, pre-operative magnetic resonance imaging (MRI) scans of IDH1/2-wildtype glioblastoma patients from The Cancer Imaging Archive (TCIA), all of whom have corresponding WES/SCNA data." (PMID 33615222, 2021). "The purpose of this study was to assess the expression of CD204+ M2-polarized TAMs in glioblastomas and their relationship with CD4+TILs, Iba+microglia, and IDH1 mutation." (PMID 35201470, 2021). "A previous study demonstrated that BV was efficacious in patients with IDH1 wild type proneural glioblastoma, whereas it failed in some other treated patients." (PMID 34439613, 2021). "In Group C, adult patients with IDH1 wild-type AA or glioblastoma will receive zotiraciclib at recurrence after receiving radiation plus concurrent TMZ followed by adjuvant TMZ." (PMID 34207158, 2021). "Recent studies have focused on the crosstalk between BCATs and IDH1 in the catabolism of glioblastoma." (PMID 33493139, 2021). "The relationship between age, IDH1 mutation, and MGMT promoter methylation in glioblastoma patients and one-year recurrence-free interval." (PMID 34257620, 2021). "Classic genetic analyses in glioblastoma have shown that IDH1 mutation, MGMT promoter methylation, 1p/19q codeletion, G-CIMP methylation, BRAFV600E mutation, and H3K27 mutation are associated with glioblastoma overall survival." (PMID 34732244, 2021). "PI3K, EGFR, IDH1 and IDH2 mutations are examples of factors that alter the glioblastoma epigenome to confer increased growth and resistance to therapy." (PMID 34769339, 2021). "While wildtype IDH1 is present in 90% of primary glioblastomas, mutant IDH1 is common in secondary glioblastomas and associated with increased patient survival." (PMID 34257620, 2021). "First, majority of our metastases class were from lung cancer followed by breast and melanoma and our glioblastoma patients all were IDH1-wildtype." (PMID 34262079, 2021). "Herein, we performed in vitro and in vivo experiments, six human IDH1/2 wild-type glioblastoma stem-like cells (GSCs) were established and studied to further determine a potential interaction of YKL-40 and MGMT promoter methylation." (PMID 32820151, 2020). "Glioblastoma and oligidendrioglioma patients with mutant IDH1 survive more than patients with the normal gene." (PMID 33552543, 2020).
glioblastoma (continued). "In IDH1 mutant glioblastoma, BCAT1 is transcriptionally suppressed because of the hypermethylation of three CpGs in the promoter, and this is also the consequence of IDH1 mutation-induced 2-hydroxyglutarate (2-HG)." (PMID 33511116, 2020). "Approximately 96% of patients with glioblastomas (GBM) have IDH1 wildtype GBMs, characterized by extremely poor prognosis, partly due to resistance to standard temozolomide treatment." (PMID 32942564, 2020). "The pre-glioblastoma subtype within isocitrate dehydrogenase 1 (IDH1) mutant gliomas express low BMP4, in comparison to early progenitor-like and neuroblastic subtypes, and is associated with a poor patient prognosis." (PMID 32102285, 2020). "The current results indicated that XGBoost is superior to other methods for predicting MGMT genotype in patients with IDH1 wildtype glioblastomas." (PMID 32942564, 2020). "In this paper we reported the analysis of patient overall survival (OS) in associations with PD-L1, IDH1 and MGMT status in anaplastic astrocytoma and glioblastoma patient receiving standard therapy." (PMID 33282092, 2020). "These immunohistochemical findings showed that both wild-type IDH1 and normal 1p/19q status supported a diagnosis of de novo-type (primary) glioblastoma in all patients." (PMID 32149081, 2020). "In glioblastomas, WT1 significantly associates the poor prognostic variables including old age, IDH1 negativity, and high Bcl2 and Ki67 labelling indices." (PMID 32856872, 2020). "While the level of MK2 expression did not correlate with the tumor grade, patient age or gender, MK2 was strongly expressed in secondary (p = 0.009; chi-square test) and IDH1-positive (p = 0.013; chi-square test) glioblastomas." (PMID 32168910, 2020). "The interesting differences in the gene expression profile between leukemia and glioblastoma cells prompted us to determine the inhibitory potential of the tested compounds against the mutant IDH1 enzyme." (PMID 32110969, 2020). "IDH1/2 mutations occur in 53% to 83% of grade II/III astrocytomas and oligodendrogliomas and in 54% of secondary glioblastoma, but only in 6.3% of primary glioblastomas." (PMID 33053763, 2020). "Mutations of a single arginine in the catalytic site of IDH1 and IDH2 were observed in several malignancies, including glioblastoma, acute myeloid leukemia (AML) and cholangiocarcinoma, leading to a gain-of-function." (PMID 32610612, 2020). "Among 14 patients with IDH1 or IDH2 mutations, the median OS was reported to be 31 months, as compared to 15 months in 115 patients with IDH1 wild-type primary glioblastoma tumors." (PMID 32987955, 2020). "This led to the assumption that 2-HG produced by mutant IDH1 can induce CIMP in a small proportion of BRAF-mutant MSS CRCs, a mechanism that was observed in glioblastoma and is associated with poor prognosis." (PMID 32610612, 2020). "In fact, a meta-analysis comparing IHC with DNA sequencing in 1360 cases of glioblastoma showed that the pooled sensitivity and specificity for IDH1 IHC were 1.00 (95% CI 0.82–1.00) and 0.99 (95% CI 0.96–1.00), respectively." (PMID 33247679, 2020). "One case was classed as diffuse leptomeningeal glioneuronal tumor (DLGNT) (patient 30), and two as glioblastoma, IDH1/2 wild type (GBM_IDH_WT) (patients 26 and 28)." (PMID 31677015, 2020). "Somatic mutations in the IDH genes (IDH1 and IDH2) were first discovered in human glioblastomas and are associated with better overall survival." (PMID 32295254, 2020). "To investigate the links between the IDH1 mutation and perturbed metabolism in more detail, we cultured six IDH1 (R132H) mutant replicate dishes of glioblastoma cells and six IDH1 wild-type LN18 glioblastoma replicate dishes of cells." (PMID 32433536, 2020).
glioblastoma (continued). "The presence of FGFR gene fusion was investigated as a target for therapy despite its low frequency (3.5%) in glioblastoma which is exclusive to IDH1/2 wild-type tumors." (PMID 33202642, 2020). "Isocitrate dehydrogenase (IDH1/2) mutations and O6-alkylguanine DNA methyltransferase (MGMT) promoter methylations are acknowledged survival predictors in patients with glioblastoma (GB)." (PMID 34966832, 2020). "IDH1 can be used as biomarker for secondary glioblastomas in addition to several newly identified key biomarker genes, such as PRDX1, based on Support Vector Machine Learning using differentially expressed genes." (PMID 31952211, 2020). "These previous reports are consistent with the growth-promoting effects of MDK on E&F-independent IDH1-wt glioblastomas with high mesenchymal activity." (PMID 32120790, 2020). "The highest performance of predicting IDH1 genotype with AUC of 0.96 was observed with a RF model that was trained with conventional MRI, but this study focused only on patients with glioblastomas." (PMID 33121211, 2020). "Mutations in isocitrate dehydrogenase genes IDH1 and IDH2 are frequently found in diffuse and anaplastic astrocytic and oligodendroglial tumours as well as in secondary glioblastomas." (PMID 32382048, 2020). "Overexpression of mutant IDH1 (R132H) in glioblastoma cells reduces NADPH and GSH levels leading to elevated ROS levels." (PMID 32408513, 2020). "Using whole-genome sequencing and mutational analysis, Parson and colleagues identified recurrent mutations in IDH1 and IDH2 at high frequencies in WHO grade II and III astrocytomas, oligodendrogliomas, oligoastrocytomas, as well as in glioblastomas." (PMID 31242696, 2019). "Octyl-(R)-2-hydroxyglutarate (Octyl-2HG), which is a membrane-permeable precursor form of the oncometabolite (R)-2-hydroxyglutarate (R-2HG) produced in IDH1-mutant tumor cells, significantly increased HDACi resistance in glioblastoma cells." (PMID 31151327, 2019). "Based on these observations and the other baseline characteristics, we expect that the study cohort and study results are representative for patients with glioblastoma, IDH1 wildtype, according to the new classification system." (PMID 31603915, 2019). "Using independent cohorts of IDH1/2- wild type glioblastoma, we also showed that these two patterns of DNA methylation can be used as molecular markers of long-term survival glioblastoma." (PMID 31159876, 2019). "Particularly, survival prediction of glioblastoma based on combination of IDH1 and MGMT methylation status outperforms the prediction by either of the biomarkers." (PMID 31150499, 2019). "A reduced proliferation rate upon transduction with mutant IDH1 has been reported in glioblastoma cells before, but our results suggest that this is independent of 2-HG accumulation." (PMID 31888244, 2019). "The salient genomic feature that largely distinguishes LGG from glioblastoma is the mutational status of the two genes encoding the isoforms of isocitrate dehydrogenase (IDH1/2); ~80% of LGG harbor IDH mutations, compared to only ~5% of glioblastomas." (PMID 31632393, 2019).